MVB12B (multivesicular body subunit 12B)
Description:
Component of the ESCRT-I complex, a regulator of vesicular trafficking process. Required for the sorting of endocytic ubiquitinated cargos into multivesicular bodies.
Synonyms: C9orf28; FAM125B; FLJ00001
Tractability: Antibody: UniProt places it where antibodies can reach, with high confidence; its Gene Ontology location is reachable by antibodies, with high confidence. PROTAC: ubiquitination databases record sites on it; its protein half-life has been measured.
Gene: Protein-coding gene on chromosome 9 (126,326,815 to 126,507,041, forward strand). Ensembl gene ENSG00000196814.
Subcellular location: Endosome; Late endosome membrane
Subcellular location (Human Protein Atlas): Vesicles; Primary cilium; Primary cilium tip; Primary cilium transition zone
Pathways (Reactome):
Disease: Budding and maturation of HIV virion; HCMV Late Events; Membrane binding and targetting of GAG proteins
Autophagy: Late endosomal microautophagy
Vesicle-mediated transport: Endosomal Sorting Complex Required For Transport (ESCRT)
Gene Ontology:
Molecular function: lipid binding; protein binding; ubiquitin binding
Biological process: regulation of epidermal growth factor receptor signaling pathway; viral budding; virus maturation; ubiquitin-dependent protein catabolic process via the multivesicular body sorting pathway
Cellular component: cytosol; early endosome; ESCRT I complex; extracellular exosome; late endosome; nucleus; plasma membrane; vesicle; endosome membrane; cytoplasm; endosome; late endosome membrane
Genetic constraint (gnomAD): Loss-of-function variants: 10 observed, 33.36 expected, observed/expected ratio (o/e) 0.3, 90% interval 0.18 to 0.51. The upper end of that interval is the gene's LOEUF score, 0.51, which puts it in group 2 of 6, group 1 being the genes least tolerant of losing a copy. Missense variants: 255 observed, 354 expected, observed/expected ratio (o/e) 0.72, 90% interval 0.65 to 0.8. Synonymous variants: 122 observed, 131.19 expected, observed/expected ratio (o/e) 0.93, 90% interval 0.8 to 1.08.
Homologues: Orthologues: dog MVB12B (99% identical), pig MVB12B (99% identical), mouse Mvb12b (96% identical), chimpanzee MVB12B (93% identical), guinea pig MVB12B (91% identical), rat Mvb12b (91% identical), macaque MVB12B (90% identical), rabbit MVB12B (89% identical), tropical clawed frog mvb12b (80% identical), zebrafish mvb12ba (72% identical), zebrafish mvb12bb (42% identical).
Diseases named in the same sentence as MVB12B in open-access papers:
MVB12B is named in the same sentence as 12 diseases in open-access papers, as found by Europe PMC text mining. Sharing a sentence is not in itself a finding about the gene and the disease. The quoted sentences say what the papers report.
neuropathy (3 papers, 2024 to 2025). A disorder affecting the nervous system that manifests with pain, tingling, numbness, and/or muscle weakness. "At this time, rs604349 in MYBPHL and rs2032930/rs2032931 in the RMI2 gene appear to be of importance in increasing the risk for developing neuropathy, while rs917778 in MVB12B and rs2234753 in the RXRA gene might reduce the likelihood of this complication." (PMID 38928135, 2024). "Two other variants (rs917778 of the MVB12B and rs2234753 of the RXRA genes) appeared to have a protective effect against neuropathy, reducing the risk to 0.07–0.08." (PMID 38339094, 2024).
glaucoma (2 papers, 2014 to 2025). Increased pressure in the eyeball due to obstruction of the outflow of aqueous humor. "Replicated associations included for instance that between rs10774625 (nearest gene: SH2B3/ATXN2) and coeliac disease, and that between rs12350420 (nearest gene: MVB12B) and glaucoma." (PMID 40493586, 2025).
cutaneous melanoma (1 paper, 2025). A primary melanoma arising from atypical melanocytes in the skin. "Genetic variations in PIP5K1C and MVB12B, which are part of the endosome-related pathway, have been linked to survival outcomes in cutaneous melanoma." (PMID 40746552, 2025). "Furthermore, genetic variants in PIP5K1C and MVB12B, components of the endosomal pathway, have been identified as novel prognostic markers for cutaneous melanoma-specific survival." (PMID 40746552, 2025).
glioma (1 paper, 2021). A benign or malignant brain and spinal cord tumor that arises from glial cells (astrocytes, oligodendrocytes, ependymal cells). "Our study has revealed causal evidence for three novel genes (RETREG2, FAM178B and MVB12B) associated with glioma risk." (PMID 33504897, 2021). "RETREG2 (or FAM134A), FAM178B and MVB12B appear to be novel findings related to glioma risk." (PMID 33504897, 2021). "The MR and colocalisation results suggested that genetically predicted increased gene expression of 12 genes were associated with glioma, GBM and/or non-GBM risk, three of which are novel glioma susceptibility genes (RETREG2/FAM134A, FAM178B and MVB12B/FAM125B)." (PMID 33504897, 2021).
cancer (2 papers, 2012 to 2022). A tumor composed of atypical neoplastic, often pleomorphic cells that invade other tissues. "Still, there were several proteins which harbored very good statistics, but lacked previous evidence to link them to cancer status, such as Protein AMBP (alternative name, alpha-1-microglobulin), Multivesicular body subunit 12B and V-type proton ATPase 116 kDa subunit." (PMID 23284758, 2012).
neurodevelopmental disorder (1 paper, 2016). A behavioral and cognitive disorder with onset during the developmental period that involves impaired or aberrant development of intellectual, motor, or social functions. "We identified genes containing CNVs previously considered to be VOUS to be new candidate genes for neurodevelopmental disorders (GIT1, MVB12B and PPP1R9A) demonstrating the utility of this strategy to index the clinical effects of CNVs." (PMID 27363808, 2016).
MVB12B also shares sentences with these, for which no sentence is quoted: autoimmune disease (1 paper); coeliac disease (1); COVID-19 (1); developmental delay (1); tumor (1); type 2 diabetes (1).